CFTR (CF transmembrane conductance regulator)
Diseases named in the same sentence as CFTR in open-access papers (continued):
Sharing a sentence is not in itself a finding about the gene and the disease.
cystic fibrosis (continued). "ABCC transporters contain 13 full molecules, including the cystic fibrosis transmembrane conductance regulator (CFTR) protein, also known as ABCC7, which causes cystic fibrosis; cell-surface receptors, such as the sulfonylurea receptors (ABCC8, ABCC9) and the multidrug resistance proteins (MRPs)." (PMID 30563187, 2018). "Cystic fibrosis is an inherited genetic disease caused by mutations of the CFTR gene." (PMID 30469013, 2018). "Cystic fibrosis is a classical autosomal recessive genetic disease, caused by loss-of-function mutations in a single gene, that which encodes the cystic fibrosis transmembrane conductance regulator (CFTR)." (PMID 30152709, 2018). "This technique was then combined with adeno-associated virus-mediated gene targeting of the cystic fibrosis transmembrane conductance regulator (CFTR) gene to generate a transgenic ferret model of cystic fibrosis and create the first reported ferret genomic bacterial artificial chromosome library." (PMID 30018107, 2018). "Interestingly, cystic fibrosis transmembrane conductance regulator (CFTR), a chloride ion selective ion channel which mutation causes cystic fibrosis, binds not only to myosin VI but also directly interacts with LMTK2." (PMID 29631601, 2018). "Mutations in the CFTR gene cause cystic fibrosis, the most common inherited disease in Caucasians1." (PMID 30158635, 2018). "Cystic fibrosis is the most common genetic disease in the white population and results from mutations in a single gene encoding for a 1480 residue transmembrane glycoprotein, the cystic fibrosis transmembrane conductance regulator (CFTR)." (PMID 29849481, 2018). "Cystic fibrosis is the most common genetic disorder that causes a significant damage in secretory epithelial cells due to the defective ion flux across the cystic fibrosis transmembrane conductance regulator (CFTR) Cl- channel." (PMID 30618777, 2018). "The availability of our model is of great importance for developing new therapeutic approaches towards WD, especially when compared to the information gained on deltaF-cystic fibrosis transmembrane conductance regulator (CFTR) mutation that cause cystic fibrosis in 90% of the patients." (PMID 29674751, 2018). "The epithelial sodium channel (ENaC) is of interest, as it plays a critical role in Cystic Fibrosis, a genetic condition caused by mutations in the gene encoding CFTR, a chloride channel that also regulates other ion conductance, namely through ENaC, across epithelia." (PMID 29500467, 2018). "For proteins involved in disease, this information can also provide invaluable insights into personalized medicine strategies, as exemplified by the customized therapies recently developed to treat cystic fibrosis patients with different disease alleles of the CFTR gene." (PMID 29794150, 2018). "Together with the large library of cystic-fibrosis-phenotypic mutations in synthetic CFTR helical hairpins at hand, this constitutes a promising platform for the quantitative analysis of CFTR transmembrane domain misfolding and the impact of drug-rescue effects." (PMID 30302398, 2018). "Ivacaftor is a drug used to treat cystic fibrosis patients carrying specific gating CFTR mutations." (PMID 30140228, 2018). "The cystic fibrosis transmembrane conductance regulator (CFTR) gene causes cystic fibrosis." (PMID 30578220, 2018). "The promiscuity of Lumacaftor for correcting various cystic fibrosis-causing mutants, with high selectivity reported for the CFTR protein, implies that there may be multiple mechanisms or binding sites at play." (PMID 30302398, 2018). "Cystic fibrosis is the most common autosomal recessive genetic disease characterized by multiorgan pathology and significantly decreased life expectancy caused by the impaired function or expression of CFTR." (PMID 30618777, 2018).
cystic fibrosis (continued). "In cystic fibrosis, the most common recessively inherited disorder, the disease is caused by changes in a specific gene, the Cystic Fibrosis transmembrane conductance regulator (CFTR) gene, resulting in an increase in viscosity of mucous secretions especially in the lungs and pancreas." (PMID 28517988, 2017). "Cystic Fibrosis is a severe genetic disorder caused by mutations in the gene coding for CFTR." (PMID 28640808, 2017). "According to the label, if the patient's genotype is unknown, an FDA-approved cystic fibrosis mutation test should be used to detect the presence of a CFTR mutation." (PMID 28804651, 2017). "Rather, the technology growth cycle was initiated by earlier research on biological processes that are associated with this protein, and the association of this locus with Cystic Fibrosis, and was already advancing exponentially when CFTR, itself, was identified." (PMID 28481922, 2017). "As discussed in Chapter “Cystic Fibrosis: a clinical view”, mutations in the CFTR gene cause CF." (PMID 27714410, 2017). "Dysfunction of CFTR causes the common, life-shortening disease cystic fibrosis." (PMID 28510592, 2017). "A study by Schneider and colleagues found that coinheritance of cystic fibrosis causing CFTR variants with SPINK1 variants significantly increases the risk of idiopathic chronic pancreatitis, with 36% of the 53 patients with cystic fibrosis having a SPINK1 mutation." (PMID 29515728, 2017). "However, incomplete 3D structural information on the unique ABC ion channel, CFTR, hinders elucidation of its functional mechanism and correction of cystic fibrosis causing mutants." (PMID 28640808, 2017). "Cystic fibrosis is caused by mutations that disrupt the plasma membrane expression, stability, and function of the cystic fibrosis transmembrane conductance regulator (CFTR) Cl− channel." (PMID 28087700, 2017). "Cystic fibrosis is the most frequent hereditary genetic disease in the Caucasian population, originating from mutations within the Cystic Fibrosis Transmembrane Conductance Regulator (CFTR) gene." (PMID 28713772, 2017). "Abnormal glucose levels are often seen in cystic fibrosis, a systematic disease caused by mutations of the CF transmembrane conductance regulator (CFTR), and in polycystic ovarian syndrome (PCOS), an endocrine disorder featured with hyperandrogenism affecting 5–10% women of reproductive age." (PMID 29204121, 2017). "CFTR ΔF508 is the most common cystic fibrosis causing genetic mutation." (PMID 28503151, 2017). "High heterogeneity in the CFTR gene mutations disturbs the molecular diagnosis of cystic fibrosis." (PMID 29178639, 2017). "Cystic fibrosis is caused by mutations in CFTR anion channels." (PMID 28419121, 2017). "A significant increase in FXYD5 was found also in the lungs and nasal epithelium of cystic fibrosis mice, at the level of both protein and mRNA, and this up-regulation was directly correlated with loss of Cystic fibrosis transmembrane conductance regulator (CFTR) function." (PMID 27066483, 2016). "In cystic fibrosis, CFTR dysfunction causes significant morbidity/mortality." (PMID 27278076, 2016). "Thus a new and more convenient approach, based on in vivo imaging analysis, has been set up to evaluate the inflammatory response in the lung of CFTR-deficient mice, a murine model of cystic fibrosis." (PMID 27468800, 2016). "To gain more confidence of using the RS-1 supplementation to improve nuclease-mediated knock-in efficiency in the embryos, we tested Cas9-mediated knock-in of CFTRdelF508, the most frequent mutation type identified in human cystic fibrosis patients, to the rabbit CFTR locus." (PMID 26817820, 2016). "In humans the opportunistic pathogen P. aeruginosa can thrive under microaerophilic to anaerobic conditions in the lungs of patients suffering from cystic fibrosis, a genetic disorder caused by mutations in the cystic fibrosis transmembrane conductance regulator (CFTR) gene." (PMID 26821182, 2016).
cystic fibrosis (continued). "This study addressed the CFTR mutations in Egyptian patients with cystic fibrosis." (PMID 27347467, 2016). "Cystic fibrosis is a genetic disease caused by mutations in the gene encoding CFTR." (PMID 27732613, 2016). "Cystic fibrosis is caused by mutations to the CFTR chloride channel." (PMID 26755333, 2016). "Another example of a mutation with phenotypic effects spanning different biological “domains” is the cystic fibrosis transmembrane conductance regulator gene (CFTR) ΔF508 mutation causing cystic fibrosis, a disease of the lung that is also associated with male infertility." (PMID 27435222, 2016). "In 2012, a new era of precision medicine in cystic fibrosis therapeutics began with the licensing of a small molecule, ivacaftor, which successfully targets the underlying defect and improves CFTR function in a subgroup of patients in a genotype-specific manner." (PMID 26403534, 2015). "Haplotypes formed by CFTR variants in six cystic fibrosis patients." (PMID 25739099, 2015). "Similarly, in-frame indels are often considered neutral or not stratified in anyway by other tools, yet important disease causative in-frame indels, such as F508del-CFTR—the most common cause of cystic fibrosis—are well established." (PMID 25706643, 2015). "Dysfunctional CFTR causes the common lethal genetic disease cystic fibrosis." (PMID 26229102, 2015). "Mutations in CFTR cause the common, autosomal recessive disease cystic fibrosis, which is characterized by high salt levels in the sweat and the accumulation of thick, sticky mucus, which is associated with inflammation, tissue fibrosis, and impaired lung, intestinal, and pancreatic function." (PMID 26184320, 2015). "Furthermore, the combination of a potentiator and a corrector (ivacaftor and lumacaftor) received US Food and Drug Administration (FDA) approval in 2015 for use in people with cystic fibrosis caused by the most common CFTR mutation, Phe508del." (PMID 26403534, 2015). "Cystic fibrosis is the most common lethal autosomal recessive inherited chronic disease in the Caucasian population and is caused by mutations in the cystic fibrosis transmembrane conductance regulator (CFTR, 7q31)." (PMID 26185365, 2015). "Mutations in the CFTR gene cause Cystic Fibrosis, an autosomal recessive genetic disease that causes progressive loss of lung function and death in the 3rd decade of life due to a decrease in airway surface liquid and reduced mucociliary transport, leading to chronic bacterial lung infections." (PMID 26018799, 2015). "The occurrence of ‘coverage gaps’ with conventional exome sequencing and their subsequent targeting by ACE is illustrated in RPGR, a gene in which over 300 mutations are implicated in retinitis pigmentosa; and CFTR, a gene in which >1,000 mutations are associated with cystic fibrosis." (PMID 26269718, 2015). "Cystic fibrosis is caused by mutations in the CFTR chloride channel." (PMID 26183966, 2015). "Cystic fibrosis is a complex multisystem disease caused by mutations in the CF transmembrane conductance regulator (CFTR) gene, leading to dehydrated luminal secretions and impaired secretion clearance, affecting mainly the respiratory and gastrointestinal tract." (PMID 26484665, 2015). "The paradigm example is cystic fibrosis, which is caused by mutations of the CFTR chloride channel." (PMID 25769815, 2015). "Cystic fibrosis or mucoviscidosis is a multi-system monogenetic disease caused by mutation of the cystic fibrosis transmembrane regulator (CFTR) gene leading to abnormal folding and function of the CFTR protein, which is a chloride/bicarbonate channel." (PMID 26542299, 2015). "The Cystic Fibrosis Mutation Database lists more than 1900 different mutations in the CFTR gene." (PMID 25803445, 2015).
cystic fibrosis (continued). "We demonstrated the accuracy of this method by phasing members of trios (revealing 100% concordance with inheritance information), and demonstrate a common clinical application by phasing CFTR alleles at genomic distances of 11–116 kb in the genomes of cystic fibrosis patients." (PMID 25739099, 2015). "The variant c.2562T > G was reported to cause altered splicing in CFTR, the cystic fibrosis gene." (PMID 26547235, 2015). "We analyzed genomic DNA derived from cell lines from six cystic fibrosis patients; each of these patients was previously known to be heterozygous for two to four CFTR variants (nine variants total, across the six patients, because several variants were shared by multiple patients)." (PMID 25739099, 2015). "Cystic Fibrosis is the most common autosomal recessive genetic disease in Caucasians caused by mutations in the Cystic Fibrosis Transmembrane Conductance Regulator (CFTR) gene." (PMID 26075213, 2015). "Cystic fibrosis is the most common lethal genetic disorder in Caucasians caused by a mutation in the gene encoding the cystic fibrosis transmembrane conductance regulator (CFTR)." (PMID 25866809, 2015). "Cystic fibrosis is an autosomal recessive disease caused by mutations in a single large gene on chromosome 7 encoding the cystic fibrosis transmembrane conductance regulator (CFTR) protein, a complex chloride channel and regulatory protein found in all exocrine tissues." (PMID 25803445, 2015). "Cystic fibrosis is a genetic disorder caused by mutations in the CFTR gene, resulting in a multisystem disease dominated by pulmonary symptoms and the establishment of chronic pulmonary infections with bacteria, e.g. Staphylococcus aureus, Haemophilus influenzae, and Pseudomonas aeruginosa." (PMID 26212271, 2015). "Cystic fibrosis is a multisystem disease caused by mutations in the cystic fibrosis transmembrane conductance regulator (CFTR) gene, which codes for a phosphorylation and nucleotide activated anion channel, resulting in altered transcellular chloride and bicarbonate transport." (PMID 27025615, 2015). "CFTR loss of function is the basic defect in cystic fibrosis." (PMID 26121472, 2015). "Cystic fibrosis is an autosomal recessive disease that results from mutations in the CFTR gene." (PMID 26504250, 2015). "In the case of a specific cystic fibrosis-associated mutation, simply increasing the amount of successfully folded mutant CFTR improves chloride conductance in cultured cells, suggesting that the particular misfolding mutation does not abolish protein function but rather amount of available protein." (PMID 24505460, 2014). "Cystic fibrosis clinically manifests with various levels of severity, which are thought to be modulated by mutations in the cystic fibrosis transmembrane conductance regulator gene (CFTR), modifier genes, and the environment." (PMID 24593045, 2014). "Cystic fibrosis is caused by mutations in the CFTR gene that predispose the airway to infection." (PMID 25071935, 2014). "We aimed at studying insulin signal transduction in cystic fibrosis and wild-type cells to establish differences and investigate whether insulin sensitivity was altered in cystic fibrosis and related to CFTR loss of function." (PMID 25299696, 2014). "TDP-43 prefers to bind to UG-rich sequences of single-stranded RNA as demonstrated by its binding at the UG-repeats near exon 9 for splicing silence of the human CFTR gene, which encodes cystic fibrosis transmembrane conductance regulator and is linked to cystic fibrosis." (PMID 24464995, 2014). "Cystic fibrosis is an inherited multi-organ disorder caused by mutations in the CFTR gene." (PMID 25216340, 2014). "Cystic fibrosis is caused by mutations in the cystic fibrosis transmembrane regulator gene (CFTR)." (PMID 24586523, 2014). "The study concentrates initially on F508del-CFTR, a very common cystic fibrosis mutation." (PMID 25405339, 2014).
cystic fibrosis (continued). "Cystic fibrosis is the most common life-threatening inherited recessive disease in the white population, and is caused by mutations in the CF transmembrane conductance regulator (CFTR) gene encoding a protein involved in the homeostasis of ions and other metabolites." (PMID 25299696, 2014). "In cystic fibrosis, the ΔF508 mutation in cystic fibrosis transmembrane regulator (CFTR) protein, which occurs in 70% of cystic fibrosis patients, has a decreased stability compared to WT, leading to a decrease in the functional protein concentration in vivo and hence net decreased function." (PMID 25340340, 2014). "Those may be of potential value for the treatment of diseases associated with decreased (cystic fibrosis) or increased (cholera toxin-induced secretory diarrhea) CFTR chloride currents." (PMID 23921386, 2013). "In cystic fibrosis, a disease caused by mutations in the CF transmembrane conductance regulator (CFTR) protein, exaggerated airway epithelial IL-8 production leads to persistent neutrophilic inflammation, a serious and presently untreated feature of CF airway disease." (PMID 23977375, 2013). "Cystic fibrosis is a life-shortening genetically inherited disease caused by mutations that alter the expression and/or the activity of the CF Transmembrane conductance Regulator (CFTR) protein." (PMID 24204804, 2013). "Mutations in cystic fibrosis transmembrane conductance regulator (CFTR) protein cause cystic fibrosis, a disease characterized by exaggerated airway epithelial production of the neutrophil chemokine interleukin (IL)-8, which results in exuberant neutrophilic inflammation." (PMID 23977375, 2013). "Cystic Fibrosis is a lethal autosomal recessive disease where mutation ΔF508 (loss of phenylalanine residue at position 508) in the gene encoding Cystic Fibrosis Transmembrane Conductance Regulator (CFTR) is responsible for the abnormal mucus secretions." (PMID 24421769, 2013). "Cystic fibrosis is a genetic disease caused by mutations in CFTR." (PMID 23555857, 2013). "However, in searching for strategies to intervene with misfolded dysferlin, we identified similarities to approaches used to unfold mutated cystic fibrosis transmembrane regulators (CFTR), the membrane protein affected in cystic fibrosis." (PMID 23185377, 2012). "CFTR is an epithelial chloride channel that is mutated in cystic fibrosis patients." (PMID 22532795, 2012). "The symptoms of cystic fibrosis include progressive respiratory dysfunction due to persistent and repeated cycles of infection and inflammation, and are caused by mutations in the cystic fibrosis transmembrane conductance regulator (CFTR) gene." (PMID 22988441, 2012). "Next to PKA, Epac has also been shown to activate CFTR in response via activation of Rap2 In models of cystic fibrosis, a disease associated with mutations in the CFTR gene, overexpression of wildtype CFTR resulted in an organised cAMP compartmentalization and restored fluid homeostasis." (PMID 24281338, 2012). "The function(s) carried over by MPs could be direct, via MP-packaged therapeutic proteins, or indirect, via specific mRNAs, such as the mRNA encoding the wild-type CFTR for the correction of the defective chloride channel function in cystic fibrosis." (PMID 23284987, 2012). "Disruption of CFTR function occurs in cystic fibrosis as a result of genetic mutations." (PMID 23272037, 2012). "Mutations in the CFTR encoding gene cause the lethal autosomal recessive disorder cystic fibrosis." (PMID 23284872, 2012). "Cystic fibrosis-associated mutations have been found in every domain of CFTR (see text footnote 1)." (PMID 22973227, 2012). "CFTR is an epithelial chloride channel that is involved in Cystic Fibrosis when mutated; thus a better knowledge of its functional interactome may help to understand the pathophysiology of this complex disease." (PMID 22514683, 2012).